HMGB1 (high mobility group box 1)
Diseases named in the same sentence as HMGB1 in open-access papers (continued):
Sharing a sentence is not in itself a finding about the gene and the disease.
Stroke (continued). "Researchers have shown that HMGB1 stimulates enlargement of endothelial progenitors, which boost angiogenesis; this outcome can be clogged by injection of HMGB1 siRNA 5 days post stroke." (PMID 29054968, 2017). "HMGB1 antagonist competitively inhibits HMGB1 surface binding and attenuates proinflammatory cytokine release in stroke." (PMID 28127491, 2017). "We found in the current hyperglycemic stroke experiment that pregabalin has potent anti-inflammatory properties via downregulation of the HMGB1/TLR-4 signaling pathway and attenuation of p-NF-κB expression." (PMID 28152042, 2017). "The efficacy of the antagonizing HMGB1 strategy for stroke has been established in animal experiments; however, clinical trials examining such treatments for stroke and autoimmune diseases have yet to be conducted according to ClinicalTrials.gov." (PMID 28649578, 2017). "We therefore suggest that more research with both animal and human models is needed to further confirm that HMGB1 has therapeutic potentials since initial studies proved that it promotes neurovascular repair and remodeling after stroke." (PMID 29054968, 2017). "In this study, our in vivo results showed that astrocytic HMGB1 played an essential role in the promoting effects of EE in the expression of IL-6 in the ischemic hemisphere during stroke recovery." (PMID 28845299, 2017). "In vivo knockdown of HMGB1 release by intrastriatal injection of HMGB1-shRNA 24 h before MCAO decreases infarct size and microglia activation, signifying a neurotoxic and proinflammatory role of HMGB1 after stroke." (PMID 29054968, 2017). "Studies have indicated that HMGB1 levels in the blood of stroke patients are higher as compared with matched healthy controls." (PMID 29054968, 2017). "PI3K/AKT signaling pathway was involved in HMGB1-induced IL-6 production from astrocytes in enriched mice during stroke recovery." (PMID 28845299, 2017). "The release of DAMPs such as HMGB1 by neurons (passive) and astrocytes (active transport) was detected as early as 6 hr after onset until day 21 after stroke." (PMID 28127491, 2017). "We suggest that more research with both animal and human models is needed to further confirm that HMGB1 has therapeutic potential since initial studies proved that it promotes neurovascular repair and remodeling after stroke." (PMID 29054968, 2017). "HMGB1–AKT–IL-6 signaling pathway was involved in EE-mediated promotion of post-stroke angiogenesis and functional recovery." (PMID 28845299, 2017). "In the acute phase after stroke, HMGB1 plays an important role in the induction of inflammation in ischaemic brain tissue mainly through microglial activation." (PMID 29245967, 2017). "EE mice treated with high-mobility group box-1 (HMGB1) inhibitor glycyrrhizin had an increased post-stroke depression and anxiety-like behavior, and the angiogenesis and functional recovery were decreased." (PMID 28845299, 2017). "In MCAO model of stroke, i.v. administration of GL significantly reduced infarct volumes, showing neuroprotection via anti-inflammatory property by inhibiting HMGB1 secretion." (PMID 28127491, 2017). "Typically, HMGB1 was described at the very early phases of stroke, whilst Prx was found at the subacute phase, mainly in the penumbral area." (PMID 27898011, 2016). "HMGB1 is involved in a number of systemic vascular diseases, is increased in stroke, and found around amyloid plaques and NFTs in AD brains, where thrombin and prothrombin accumulate as well." (PMID 27553758, 2016). "High levels of HMGB1 have been reported in the serum of patients who had suffered from stroke 7 days previously." (PMID 27596007, 2016). "Fourth, Gly injection in vivo inhibited HMGB1 release in CSF and serum after stroke, and an in vitro assay showed that Gly inhibited T cell proliferation stimulated by HMGB1." (PMID 27609334, 2016). "Among them, several studies in the last years investigated the HMGB1 in human stroke patients as a pro-inflammatory biomarker." (PMID 27898011, 2016).
Stroke (continued). "Second, we used Western blotting to examine protein levels of HMGB1 in the CSF collected 3 days post-stroke, and the results show that HMGB1 levels were robustly increased in the CSF after stroke but were significantly blocked by Gly." (PMID 27609334, 2016). "We also measured the expression change profile of TLR2 in response to in vitro HMGB1 stimulation to show the role of TLR2 in monocyte activation in stroke patients." (PMID 27040385, 2016). "Taken together, it is plausible that Gly inhibits brain injury by inhibiting T cell activity, which is at least partly mediated by HMGB1 release after stroke." (PMID 27609334, 2016). "HMGB1 protein levels were increased in the serum from 5 to 24 to 48 h after stroke, and Gly significantly blocked increases in HMGB1 at 24 and 48 h." (PMID 27609334, 2016). "Blockade of HMGB1 mediated inflammatory signaling during the acute phase of stroke is beneficial for BBB functional integrity and functional recovery." (PMID 27069533, 2016). "After stroke, cells in the hypoperfused territory become necrotic, release HMGB1, induce expansion of a monocyte subpopulation, and contribute to the immunosuppressive state in the subacute phase of stroke, predisposing patients to pneumonia." (PMID 27923376, 2016). "This study clarifies the mechanism by which hypothermia exerts its therapeutic effects and suggests that further interventions aimed at blocking the actions of HMGB1 will be valuable additions to stroke treatment regimens." (PMID 27544687, 2016). "Release of HMGB1 is observed 2–4 h after stroke onset and peaks around 4 days by activated microglia and astrocytes." (PMID 27069533, 2016). "Liesz and colleagues demonstrated that immature myeloid progenitor cells egress from the bone marrow in response to DAMPs, such as high-mobility group box 1 (HMGB1), secreted as a consequence of stroke." (PMID 26690125, 2015). "Although a reduction of HMGB1 production in the acute phase improves stroke recovery, it is vital for the induction of repair processes in the sub-acute phase." (PMID 26690125, 2015). "A recent report of elevated serum concentrations of HMGB1 in stroke patients confirmed our findings." (PMID 24594628, 2014). "Taken together, our results indicate a potential role of HMGB1 in regulating the effects of T cells in stroke-induced lymphopenia." (PMID 23555048, 2013). "This is the first review of the literature evaluating the potential of three ARBs for the HMGB1-RAGE axis on stroke therapy, including prevention and acute treatment." (PMID 24065095, 2013). "We used western blot to measure HMGB1 levels in the peripheral blood 48 h after stroke onset, and found that HMGB1 was released in the plasma in WT rats but not in nude rats (data not shown), suggesting that HMGB1 release is associated with T cells." (PMID 23555048, 2013). "A previous study reported that intravenous injection of anti-HMGB1 monoclonal antibody significantly attenuated brain edema in a rat model of stroke, possibly by attenuating glial activation." (PMID 23991202, 2013). "It is well-known that HMGB1 is a cytokine-like protein, which is released into the CSF and peripheral blood after stroke." (PMID 23555048, 2013). "It has also been shown that in stroke inhibition of HMGB1 release as well as RAGE ablation leads to a neuroprotective effect." (PMID 22227007, 2012). "The purpose of this study was to examine the correlation between changes in serum levels of HMGB1 following acute ICH and the severity of stroke as well as the underlying mechanism." (PMID 20936104, 2010). "Here we confirm and extend this previous observation since we also detected increased serum concentrations of HMGB1 by ELISA in a larger cohort of stroke patients." (PMID 20090932, 2010). "HMGB1 was rapidly upregulated following stroke and elevated serum levels persisted throughout the study period of 14 days (p = 0.0002)." (PMID 20090932, 2010).
Stroke (continued). "To better understand the role of soluble modulators in stroke induced immunosuppression we studied prototypical pro- and anti-inflammatory cytokines and determined HMGB1 levels." (PMID 20090932, 2010). "Furthermore, HMGB1 is actively secreted by activated glial and other cells 2 days after stroke, peaks on day 4, and can persist for weeks or even up to 1 month." (PMID 38740617, 2025). "Interestingly, HMGB1 plays a role in promoting vascular remodeling and functional recovery late after stroke." (PMID 38740617, 2025). "However, there are still fewer studies on the mechanism of the effect of active neuronal HMGB1 release on neuroinflammation in the central nervous system after stroke and the role of ablation of neuronal HMGB1 on ischemic brain tissue." (PMID 38740617, 2025). "Notably, plasma levels of both soluble RAGE (sRAGE) and HMGB1 were significantly increased 48 h after ischemic stroke, and sRAGE levels were an independent predictor of functional outcome 3 months after stroke." (PMID 38740617, 2025). "VPA has been associated with reduced HMGB1 levels in patients with post-stroke epilepsy, suggesting that its anti-inflammatory action may lead to secondary stabilization of the BBB by attenuating HMGB1-mediated permeability changes." (PMID 40806813, 2025). "However, mechanisms of HMGB1 in neuroinflammation and oxidative stress leading to blood–brain barrier disruption and hemorrhagic transformation after mechanical thrombectomy in stroke models need further investigation." (PMID 38740617, 2025). "The complex role of HMGB1 in ischemic stroke and the mechanism of hemorrhagic transformation need to be further investigated and provide potential targets for neuroprotective strategies after stroke." (PMID 38740617, 2025). "The reactive oxygen species-sensitive nanomedicines can effectively alleviate stroke pathology by controlling the release of therapeutic agents, inhibiting the translocation of nuclear HMGB1, and modulating microglial polarization to reduce infarct volume and enhance neurogenesis." (PMID 38740617, 2025). "Thus, the high concentration of HMGB1 has been considered as the marker of severity and a poor prognostic after stroke." (PMID 40332314, 2025). "HMGB1 promotes necroptosis and harmful inflammation in the early phase of ischemic stroke, while it plays an important role in the remodeling of the neurovascular system and the recovery of function in the late phase of stroke." (PMID 38740617, 2025). "Targeting HMGB1 is efficacious in improving clinical outcomes in stroke." (PMID 38740617, 2025). "Diet and exercise may be involved in the regulation of HMGB1 in ischemic stroke, and a low-fat diet and moderate exercise are beneficial for stroke prognosis." (PMID 38740617, 2025). "A recent study has found that platelet depletion or platelet-specific knockdown of HMGB1 significantly reduced plasma levels after stroke and greatly improved stroke prognosis, demonstrating that platelets are also a key source of HMGB1 in the plasma during ischemic stroke brain injury." (PMID 38740617, 2025). "Our findings are important and meaningful; drugs that reduce HMGB1 expression may be potential drugs for the treatment of stroke." (PMID 40128654, 2025). "This pathway may contribute to memory problems in a variety of neurological and psychiatric diseases characterized by elevated HMGB1 levels, including epilepsy, Alzheimer’s disease, and stroke." (PMID 39466324, 2025). "Additionally, AIM can bind to DAMPs, such as S100 proteins, heat shock proteins, and HMGB1, to reduce inflammation and improve outcomes in mouse models of stroke." (PMID 41162904, 2025). "If confirmed, measurement of serum HMGB1 could be incorporated into clinical evaluation of stroke patients to identify those requiring closer monitoring and preventative treatment for cognitive dysfunction." (PMID 38708343, 2024).
Stroke (continued). "HMGB1 may be a novel biomarker to identify patients likely to develop post-stroke cognitive impairment for targeted preventive interventions." (PMID 38708343, 2024). "This is further supported by evidence highlighting HMGB1’s dual role in the early inflammatory response and neurovascular remodeling during stroke recovery, underscoring the potential of targeting HMGB1 as a therapeutic strategy to reduce stroke-induced damage." (PMID 39598404, 2024). "Through the inhibition of HMGB1, GA plays a neuroprotective role by reducing inflammatory responses and supporting cellular repair mechanisms, illustrating its therapeutic potential for improving post-stroke outcomes in ischemic stroke models." (PMID 39598404, 2024). "In both experimental animal stroke models and clinical studies involving human subjects, elevated peripheral blood concentrations of HMGB1 have been observed following acute cerebral ischemia, which is thought to reflect the ongoing neuroinflammatory processes triggered by the ischemic insult." (PMID 38708343, 2024). "Additionally, the release of high-mobility group box 1 (HMGB1) by platelets can facilitate NETosis in the acute phase of stroke, exacerbating disease progression." (PMID 39337436, 2024). "Local HMGB1 concentrations are significantly increased in experimental and clinical stroke." (PMID 39582054, 2024). "In the chronic phase following a cerebrovascular accident, HMGB1 exerts detrimental effects on synaptic plasticity by attenuating long-term potentiation through its influence on NMDA receptor function, dendritic spine morphology, and neural networks that subserve learning and memory processes." (PMID 38708343, 2024). "Additionally, HMGB1 plays a crucial role in immunosuppression after stroke, which mainly features monocyte hypofunction and lymphocytopenia." (PMID 37062906, 2023). "Despite not serving as a ligand for cGAS, HMGB1 facilitates the formation of U-turns in DNA, thereby promoting cGAS-mediated innate immunity, which may prove crucial in the context of the pronounced HMGB1-induced injury observed following stroke." (PMID 37915571, 2023). "Our results suggested that the polymer-drug conjugate nanoparticles could effectively alleviate the pathology of stroke, reduce infarct volume, and enhance neurogenesis, through inhibiting HMGB1 translocation and switching microglia M1 or M2 phenotype." (PMID 35415314, 2023). "HMGB1 is initially released passively from dying neurons and subsequently secreted actively by infiltrating microglia/macrophages during the early stages of stroke." (PMID 37915571, 2023). "The latest study suggests that platelet-derived HMGB1 mediates the formation of NETs in stroke." (PMID 36892020, 2023). "HMGB1 is an important molecule released early after ischemic stroke, which plays an important role in the initiation, amplification, and dissipation of inflammation after stroke." (PMID 37062906, 2023). "Furthermore, there was a correlation between extracellular HMGB1 levels and stroke severity in the rat middle cerebral artery occlusion (MCAO) model." (PMID 36388178, 2022). "Furthermore, plasma levels of HMGB1 correlated with plasma NET levels in stroke patients, and platelet-specific knockout of HMGB1 in mice prevented stroke-induced NET formation and improved stroke outcomes." (PMID 35358095, 2022). "Twenty-four hours after stroke, neutrophil-depleted mice had similar plasma HMGB1 levels compared with neutrophil-sufficient mice (9.8 ± 3.7 ng/mL vs. 8.8 ± 2.8 ng/mL, respectively), indicating that neutrophils do not contribute to the rise of plasma HMGB1 after stroke." (PMID 35358095, 2022). "Consequently, HMGB1 released by astrocytes in the late phase of stroke promotes the viability and migration of endothelial progenitor cells leading to repair of the neurovascular unit, peri-infarct angiogenesis, and improvement in neurological function." (PMID 36232519, 2022).
Stroke (continued). "However, the current preclinical research results show that HMGB1 antagonists have positive significance in the treatment of Parkinson's disease, stroke, traumatic brain injury, epilepsy, and other diseases." (PMID 36388178, 2022). "Interestingly, overexpression of extracellular HMGB1 has been observed in clinical and preclinical studies on Parkinson's disease, stroke, traumatic brain injury, epilepsy, autism, depression, multiple sclerosis, and amyotrophic lateral sclerosis." (PMID 36388178, 2022). "Additionally, we observed increased plasma and platelet surface–expressed high-mobility group box 1 (HMGB1) in stroke patients." (PMID 35358095, 2022). "Second, we only collected samples within 24 h of stroke onset to detect the levels of HMGB1." (PMID 36421903, 2022). "Furthermore, stroke patients had elevated plasma and platelet surface-expressed high-mobility group box 1 (HMGB1)." (PMID 36293230, 2022). "Nevertheless, the role of HMGB1 in stroke goes beyond its effect on neutrophils." (PMID 35358095, 2022). "Similarly, plasma HMGB1 levels were also found to be increased in ischemic stroke patients from 24 h up to 90 days after stroke." (PMID 35971650, 2022). "However, highly raised HMGB1 levels in the blood of ischemic stroke patients have been traced up to one month after stroke." (PMID 36232519, 2022). "However, elevated levels of HMGB1 within the first 24 h after ischemic stroke are considered to be a good predictor of stroke severity and clinical outcome, thus serving as a potential therapeutic target." (PMID 36388178, 2022). "In conclusion, HMGB1 may be involved in the pathophysiology of stroke, but animal experiments have shown that HMGB1 has a biphasic effect in stroke patients, and it is unclear to what extent it promotes the development of the disease." (PMID 36388178, 2022). "This review discusses the possible mechanisms by which HMGB1 mediates Parkinson's disease, stroke, traumatic brain injury, epilepsy, autism, depression, multiple sclerosis, amyotrophic lateral sclerosis, and the potential of HMGB1 as a biomarker for these diseases." (PMID 36388178, 2022). "HMGB1 has been shown to be detected in the serum of ischemic stroke patients and in the brain tissue of mice after experimental ischemic stroke as early as two hours after stroke." (PMID 36232519, 2022). "The role of an HMGB1 inhibitor in patients with stroke remains to be determined." (PMID 34054705, 2021). "The present study demonstrated that HMGB1 is an independent risk factor for carotid plaque vulnerability in an Italian population with T2DM, representing a possible molecular target to treat unstable carotid plaques and stroke prevention." (PMID 34044825, 2021). "However, in an experimental animal stroke model, it was observed that the release of HMGB1 and signalling through RAGE contributed to brain injury–induced sickness behaviour." (PMID 33940970, 2021). "PRRs identified different pathological stimuli including endogenous damage-associated molecular patterns (DAMPs) released from damaged cells in the stroke core such as high mobility group box 1 protein (HMGB1), heat shock proteins, and peroxiredoxin family proteins." (PMID 34646128, 2021). "Among these molecules, high mobility group box 1 (HMGB1) protein appears in the early stages of stroke and is recognized by several toll-like receptors (TLRs) like TLR2 or TLR4, which trigger an inflammatory response through the release of pro-inflammatory cytokines in an NF-κB-dependent process." (PMID 34208834, 2021). "For example, an anti-HMGB1 monoclonal antibody (mAb) has been developed and was shown to be effective in treating many animal models of central nervous system (CNS) diseases, such as Parkinson’s disease, Alzheimer’s disease, and stroke." (PMID 33732708, 2021). "HMGB1 is an important chromosomal protein released outside the nucleus that binds to the receptor forming advanced glycation end products and influencing the inflammatory process after stroke." (PMID 34868302, 2021).